PIEZO1 (piezo type mechanosensitive ion channel component 1 (Er blood group))
Diseases named in the same sentence as PIEZO1 in open-access papers (continued):
Sharing a sentence is not in itself a finding about the gene and the disease.
breast carcinoma (continued). "Studies have suggested that the PIEZO1 ion channel plays a role in invasion and progression in cancer; elevated levels of PIEZO1 have been correlated with increased migration in breast cancer cells, chemo-resistance and invasion in gastric cancer cells, and increased invasion of osteosarcoma cells." (PMID 38398074, 2024). "However, opposing results regarding Piezo1 and Piezo2 roles in breast cancer exist in the literature." (PMID 39001475, 2024). "Previous studies have reported that Piezo1 is expressed in breast cancer cells." (PMID 38463518, 2024). "Further investigation into the function of PIEZO1 in breast cancer subtypes is necessary." (PMID 38398074, 2024). "Mechanistically, Piezo1 activation significantly increased the expression of NOX2 in the breast cancer cells, which may exert the antitumor effect in a ROS-dependent way." (PMID 38463518, 2024). "High PIEZO1 expression is correlated with a significant decrease in survival in HR-negative cohorts, especially in triple-negative breast cancer (TNBC), suggesting that PIEZO1 could be utilized as a prognostic biomarker in HR-negative breast cancer." (PMID 38398074, 2024). "Piezo1 acts as a critical sensor of compression stress in these cells, increasing migration and invasion of breast cancer cells by modulating the invadopodium formation and degradation of ECM through metalloproteinases by actin protrusion formation via Src signaling." (PMID 37762011, 2023). "A differential implication of Piezo1 has similarly been evidenced in breast cancer cells." (PMID 38132106, 2023). "For instance, Piezo1 is expressed at higher levels in the squamous cell carcinoma, bladder cancer, prostate cancer and breast cancer tissues compared to the corresponding normal tissues, indicating that it may be involved in cancer progression." (PMID 37306789, 2023). "Furthermore, in this study we only investigated Piezo1 for its role in mediating the breast cancer cell response to compression." (PMID 34979904, 2022). "Additionally, we identified that Piezo1 mediated these processes and the invasive phenotype of the breast cancer cells also depended on the integrity of caveolae in the cell membrane." (PMID 34979904, 2022). "Indeed, Piezo1 and Piezo2 have recently been shown to enhance invadopodia formation in breast cancer cells." (PMID 36158191, 2022). "Clinical breast cancer samples with Piezo1 high expression had fewer immunogenic characteristics, including the reduction of the activated CD4+ memory T cells and CD8+ T cells, which was associated with poor prognosis in breast cancer patients." (PMID 36230880, 2022). "In the development of new drugs, Piezo1 activation could offer a novel way to inhibit thrombinase-induced blistering in breast cancer cells." (PMID 36615408, 2022). "Piezo1 has also been shown to affect migration in breast cancer." (PMID 34831037, 2021). "Additionally, higher hazard ratios and shorter survival times were observed in breast cancer patients with primary tumors exhibiting high Piezo1 mRNA levels, indicating the role of Piezo1 in metastatic dissemination." (PMID 34831037, 2021). "In one study, breast cancer cells were able to survive in circulation as well as immune cells, which could suggest the importance of Piezo1 in this process." (PMID 34831037, 2021). "We also found that high PIEZO1 expression is correlated with worse survival outcomes in HR-negative patients, suggesting that PIEZO1 could be utilized as a prognostic biomarker in HR-negative breast cancer." (PMID 38398074, 2024). "Piezo1 might be a promising novel photothermal therapeutic target for breast cancer." (PMID 38463518, 2024). "Therefore, our goal was to determine the clinical relevance of PIEZO1 in breast cancer." (PMID 38398074, 2024). "All these have suggested that Piezo1 may be a promising novel therapeutic target for breast cancer." (PMID 38463518, 2024).
breast carcinoma (continued). "The Breast Cancer Gene-Expression Miner (bc-GenExMiner) was used as a tool for the analysis of data from many well-annotated transcriptomic datasets to obtain a comprehensive understanding of the correlation between PIEZO1 and prognostic indicators in breast cancer." (PMID 38398074, 2024). "Moreover, Piezo1 has been identified as a cancer-promoting factor in a variety of cancers, including hepatocellular carcinoma, gastric cancer, oral squamous cell carcinoma, and breast cancer." (PMID 35991548, 2022). "The same experiments carried out with 4 T1 cells (another breast cancer cell line) showed similar results as those with MDA-MB-231 cells, confirming that the compression-enhanced breast cancer cell invasion and associated Piezo1 mediation were independent of the cell lines used." (PMID 34979904, 2022). "In addition, the involvement of Piezo1 in cell motility may explain the relationship between the down-regulation of Piezo1-mediated activity in the breast cancer cell line MCF-7, resulting in decreased motility of MCF-7 cells." (PMID 33722169, 2021). "Piezo1 stimulation improves osteocytes’ mechanoresponse to LMHF vibration, thus inhibiting osteoclastogenesis and decreasing MDA-MB-231, a type of breast cancer cell, from migrating." (PMID 38390363, 2024). "The western blot analysis suggested that Piezo1 had a moderate expression in MDA-MB-231 cells and high expression in the 4T1 breast cancer cells, indicating the potential role of the Piezo1 ion channel in breast cancer." (PMID 38463518, 2024). "We also analyzed the PIEZO1 expression in cohorts differentiated by Scarff–Bloom–Richardson (SBR) grade, which reflects tumor grade and predicts prognosis in breast cancer patients." (PMID 38398074, 2024). "The results presented here demonstrate a clear intersection between cellular geometry, Ca2+ signaling, the PIEZO1 force channel, and EPI-MES plasticity in breast cancer cells." (PMID 38632473, 2024). "First, we examined survival outcomes by PIEZO1 expression between those with Stage I/II and Stage III/IV HR-negative breast cancer." (PMID 38398074, 2024). "This study showed the potential of stimulating Piezo1 in enhancing the mechanoresponse of osteocytes to LMHF vibration and further suppressing breast cancer migration via osteoclasts." (PMID 35884459, 2022). "In this study, we showed that the stimulation of Piezo1 using Yoda1 enhances the effects of LMHF vibration on osteocytes and breast cancer cells." (PMID 35884459, 2022). "To test this hypothesis, we examined in vitro cultured human breast cancer cells for their ability to invade and degrade extracellular matrix in the presence or absence of externally loaded compression, together with corresponding changes in Piezo1 and calcium signaling." (PMID 34979904, 2022). "It has been shown that the activation of Piezo1 can promote the migration of Stomach cancer, Colon tumors, HCC, breast cancer cells, and PDA." (PMID 36615408, 2022). "In the malignant human breast cancer cells MCF-7, a cellular model of primary invasive breast ductal carcinoma, the expression of Piezo1 is considerably increased compared to the MCF-10A cells, a model for normal mammary gland." (PMID 32635333, 2020). "The link between PIEZO1, cellular geometry, and EPI-MES markers could indicate a role for PIEZO1 in EPI-MES plasticity, which is Ca2+ influx-dependent in other cell types, including breast cancer cells." (PMID 38632473, 2024). "While implicated to various degrees in different types of cancers, the clinical significance of PIEZO1 has not been explored in breast cancer." (PMID 38398074, 2024). "Our study reveals that Piezo1 activation might serve as a photothermal sensitizer for PTT, which may develop as a promising therapeutic strategy for breast cancer." (PMID 38463518, 2024).
breast carcinoma (continued). "The apparent discordance between the studies regarding Piezo1 and Piezo2 correlation with aggressive phenotypes in breast neoplasms might be partly explained by the limited representativeness of the MCF-7 breast cancer cell line employed in the older study." (PMID 39001475, 2024). "Combining automated epifluorescence microscopy and a genetically encoded calcium indicator, we demonstrate that activation of the PIEZO1 force channel with the PIEZO1 agonist, YODA 1, induces features of epithelial-to-mesenchymal plasticity in breast cancer cells." (PMID 38632473, 2024). "Furthermore, the activity of Piezo1 promoted MCF-7 cells (a human breast epithelial cell line) migration and invasion, underscoring a potent role of Piezo1 in breast cancer progression." (PMID 35615675, 2022). "In a study comparing MCF-7 breast cancer cells to neoplastic MCF-10A healthy mammary glands, which lack a mechanoactivated current, MCF-7 cells expressed significantly higher levels of exogenous Piezo1 mRNA." (PMID 34831037, 2021). "In this study, we hypothesize that the stimulation of Piezo1 with Yoda1 enhances the mechanoresponse of osteocytes to LMHF vibration, inhibiting the formation of osteoclasts and further reducing the migration of breast cancer cells." (PMID 35884459, 2022). "Therefore, our results suggest that PIEZO1 primarily contributes to worse survival outcomes in HR-negative patients and specifically in TNBC, implying that PIEZO1 may have different effects in different subtypes of breast cancer." (PMID 38398074, 2024). "However, the clinical impact of PIEZO1 in breast cancer is not well characterized." (PMID 38398074, 2024).
Hypertension (42 papers, 2018 to 2025). The presence of chronic increased pressure in the systemic arterial system. "The abundance of Piezo1 and Piezo2 mRNAs in nodose ganglia was found to be reduced in rats with spontaneous hypertension or hypertension caused by a nitric oxide synthase inhibitor or angiotensin II." (PMID 40721314, 2025). "In rats on high fat diet with fructose in the drinking water, there was hypertension associated with decreased Piezo1 mRNA and increased Piezo2 mRNA in the aortic arch." (PMID 40721314, 2025). "Endothelial-cell specific loss of NO-driven vasodilation in lead to hypertension in Piezo1-knockout mice." (PMID 39507419, 2024). "Taken together, our results suggest that Piezo1 activation caused by hypertension induced neuronal apoptosis via activating the Hippo pathway." (PMID 39328029, 2024). "In patients with risk factors of ischemic stroke like hypertension and hyperglycemia, Piezo1 is upregulated and activated in several blood cells, including platelets, red blood cells, neutrophils, and hematopoietic stem cells." (PMID 38923822, 2024). "The results showed that Piezo1 misexpression can be linked to a variety of chronic illnesses, which range from hypertension to cancer and hemolytic anemia." (PMID 39507419, 2024). "Immunofluorescence staining and calcium imaging were employed to elucidate the Piezo1 activation caused by hypertension." (PMID 39328029, 2024). "Piezo1 activation induces vasodilation, and its deficiency contributes to vascular disorders, such as hypertension." (PMID 36846322, 2023). "Interfering with the Piezo1 mechanosensitive ion channel causes hypertension by blocking shear stress driven support of vasodilatation." (PMID 36740996, 2023). "Our data demonstrate that in PVAT, PIEZO1 activation regulates adipogenesis, possibly linking hypertension with the loss of adipocyte PVAT populations." (PMID 36120469, 2022). "It was recently reported that blocking Piezo1 or TRPV4 prevented hypertension-associated vascular hyperpermeability, but the underlying mechanisms or possible interactions were not uncovered." (PMID 33298523, 2021). "Another focal adhesion associated target is PIEZO1, a mechanosensitive ion channel that is important in SMCs during arterial remodelling in hypertension." (PMID 31283468, 2019). "A smooth muscle cell-specific loss of PIEZO1 causes the deficit of arterial remodeling upon hypertension." (PMID 29757938, 2018). "The onset of hypertension is closely associated with the abnormal activation of Piezo1 in VSMCs." (PMID 41195420, 2025). "In addition, Piezo1 inhibition attenuated neuronal apoptosis caused by hypertension via inhibiting the Hippo signaling pathway in primary neurons." (PMID 39328029, 2024). "Homeostatically, PIEZO1 is highly expressed in a variety of cells in the heart, including ECs, CFs, and CMs, and regulates mechanical adaptation in various HF risk factors such as hypertension, cardiac hypertrophy, and fibrosis." (PMID 39272994, 2024). "In fact, ED is associated with high blood pressure and other cardiovascular problems, and Piezo1 dysfunction could also contribute to ED." (PMID 36846322, 2023). "Moreover, genetic polymorphisms in Piezo1 function may help explain the differences in hypertension susceptibility and drug response across different populations." (PMID 41195420, 2025). "In hypertension-related myocardial hypertrophy models, the inhibition of Piezo1 not only improved structural remodeling but also reduced the degree of myocardial fibrosis, suggesting its multi-faceted protective effects on heart function." (PMID 41195420, 2025). "Future studies should further investigate the interplay between Piezo1 signaling and downstream pathways, such as sAC-cAMP signaling, to uncover additional therapeutic opportunities for managing vascular dysfunction and hypertension." (PMID 40255319, 2025). "When activated by high pressure, Piezo1 can disrupt lung blood vessel barriers and remodel arteries in hypertension." (PMID 41249516, 2025).
Hypertension (continued). "In animal experiments, inhibiting Piezo1 not only reduces blood pressure but also alleviates hypertension-related vascular remodeling and heart damage." (PMID 41195420, 2025). "In pathological conditions like hypertension, Piezo1 expression is upregulated, leading to excessive smooth muscle cell contraction and vascular remodeling, which exacerbates the increase in blood pressure." (PMID 41195420, 2025). "For example, some studies suggest that Piezo1 is involved in mechanosensing in podocytes and renal tubular epithelial cells, potentially promoting hypertension development by affecting sodium excretion and renal blood flow perfusion." (PMID 41195420, 2025). "More notably, Piezo1’s positive feedback mechanism has an amplifying effect during the course of hypertension." (PMID 41195420, 2025). "Looking ahead, research on Piezo1 offers new insights into the mechanobiological explanation of hypertension." (PMID 41195420, 2025). "In a chronic hypertension model induced by angiotensin II (AngII), VSMC-specific PIEZO1 knockout reduces the thickness of the middle layer of blood vessels to alleviate hypertension." (PMID 39272994, 2024). "Experiments involving in vivo injections of the Piezo1 agonist Yoda1 or antagonist GsMtx4 in a mouse model of hypertension led to the conclusion that Piezo1 activation in platelets causes platelet hyperactivation and increases the risk of thrombosis." (PMID 38534326, 2024). "Hypertension and mechanical squeezing activate platelet Piezo1 and accelerate platelet clotting by upregulating PI3K/AKT and phosphatidylserine." (PMID 38923822, 2024). "VSMC mechanosensation depends on the swift opening of Piezo1, a tension‐gated ion channel that allows the influx of calcium (Ca2+) ions upon activation to regulate vascular development, blood pressure, and hypertension‐dependent arterial remodeling." (PMID 37941511, 2024). "MiR-103a, a potential biomarker of myocardial infarction, can be involved in the progression of hypertension and promote MI and HF by inhibiting PIEZO1 expression." (PMID 39272994, 2024). "The role of Piezo1 has been previously discussed in cardiovascular disease interventions, including vascular development, blood pressure, hypertension‐dependent arterial remodeling, and VSMCs with aneurysm, but it remains unexplored in chronological aging." (PMID 37941511, 2024). "The Piezo-type mechanosensitive Ion channel component 1 (Piezo1) protein has been shown to play an important role in the inflammatory response in hypertension and some diseases." (PMID 36675179, 2023). "Second, the use of Piezo1 knockout mice would contribute to a better understanding of the role of Piezo1 in AF induced by hypertension." (PMID 35252406, 2022). "This article reviews the molecular mechanism of Piezo1 in atherosclerosis, hypertension and pulmonary hypertension, in order to provide a theoretical basis for the further study of vascular remodeling." (PMID 36247424, 2022). "PIEZO1 channels are critical for vascular remodelling, including angiogenesis, and have implications for hypertension, aneurysms and stroke." (PMID 33589590, 2021). "In mice, double KO of Piezo1 and Piezo2 in the nodose and petrosal sensory ganglia abolished drug-induced baroreflex and aortic depressor nerve activity, with hypertension and increased blood pressure variability." (PMID 33935792, 2021). "It has been shown that Piezo1 is required for structural maintenance of endothelial cells, and the remodeling of vascular smooth muscle cells during hypertension." (PMID 30400259, 2018). "PIEZO1 is critically important for shear-stress induced Ca2+ signaling in endothelium, for lymphatic valve and vessel development and for hypertension-dependent arterial wall remodeling." (PMID 41279936, 2025). "In terms of intervention, Piezo1 has emerged as a potential therapeutic target for hypertension." (PMID 41195420, 2025).